SOD2 (superoxide dismutase 2)
Diseases named in the same sentence as SOD2 in open-access papers (continued):
Sharing a sentence is not in itself a finding about the gene and the disease.
cancer (continued). "Initially, SOD2 was considered a tumor suppressor gene based on its low levels in several types of cancer." (PMID 36672191, 2023). "Several studies have suggested the complicity of antioxidant enzymes in cancer development and identified high expression of SOD2 as a factor in cancer progression." (PMID 35164076, 2022). "Based on the in vitro results obtained up to this point, we decided to use circulating SOD2 as a candidate biomarker of cancer chemotherapy response." (PMID 36010852, 2022). "Four gene markers, BARD1 (BRCA-associated RING domain 1), SOD2 (superoxide dismutase 2), S100A10, and TSC22D3 (TSC22 domain family member 3), were found to be the targets of several approved cancer drugs." (PMID 36430822, 2022). "SOD2 promoter methylation was reported in both transformed and cancer cells, and in another study, cytosine methylation of the second intron of SOD2 was found to result in reduced SOD2 expression." (PMID 35164076, 2022). "Previous studies have suggested that circRNA SOD2 (CircSOD2) expression was upregulated in a number of cancers." (PMID 35188072, 2022). "In one study, curcumin oil was found to maintain SOD2 expression and delayed bile acid-enhanced esophageal injury and cancer progression." (PMID 35164076, 2022). "Secondly, it was reported that catalase prevents SOD2 overexpression-induced promotion of cancer cells in vitro and in vivo." (PMID 36552527, 2022). "Apparently, decreased SOD2 activity and hiked-up reactive oxygen species are the prerequisite for the metabolic reprogramming of cancer cells." (PMID 36009568, 2022). "Promoting ROS accumulation in cancer cells to a toxic level is the focus of some emerging cancer therapies, which makes SOD2 a good potential target." (PMID 35164076, 2022). "Many cancers have high levels of expression of SOD2, particularly in the metastatic and aggressive phenotypes." (PMID 36233276, 2022). "SOD2 can induce an increase in cellular oxidant/antioxidant ratios, correlating directly with cancer angiogenesis, progression and metastasis." (PMID 36497431, 2022). "Because radiation therapy can kill cancer cells by generating free radicals, and because SOD2 is a primary antioxidant enzyme, SOD2 can mitigate the effects of radiotherapy." (PMID 34943029, 2021). "In fact, the function of SOD2 in the development and progression of cancer is still poorly understood." (PMID 34062984, 2021). "In fact, loss of SIRT3 in human CLL cells contributes to cancer progression via hyperacetylation of the metabolic enzymes isocitrate dehydrogenase (IDH2) and superoxide dismutase 2 (SOD2)." (PMID 34828304, 2021). "Together, these studies are consistent with the notion that SOD2 level is reduced when cancer initiates and is increased during progression of the disease." (PMID 34943029, 2021). "An extensive in-depth discussion of the complex regulation of SOD2 expression and activity in cancer is beyond the scope of our study." (PMID 34062984, 2021). "For a detailed description of the many variables involved in SOD2 regulation in cancer, the reader is referred to several recent excellent reviews." (PMID 34062984, 2021). "It is known that upregulated SOD2 promotes cancer stemness and reduces apoptosis by scavenging ROS, thus mediating resistance to chemotherapy; in contrast, SOD2 inhibition impedes cancer progression." (PMID 33980809, 2021). "Elevated level of SOD2, the primary mitochondrial oxidative scavenger, was found in several cancer cells." (PMID 33980809, 2021). "In the analysis of OS, women whose carcinomas had high SOD2 expressions also presented poor OS (p = 0.003)." (PMID 34062984, 2021). "A total of 78.6% of the patients whose carcinomas showed high SOD2 expression had recurrences, while only 29.3% of patients with carcinomas expressed low SOD2 levels." (PMID 34062984, 2021).
cancer (continued). "According to the log-rank test, women with shorter DFS had carcinomas with higher SOD2 expression (p = 0.001)." (PMID 34062984, 2021). "We suspect that SIRT3 mediated SOD2 activity is specific to cancer microenvironment in DLBCL to protect cells from oxidative stress." (PMID 33273545, 2020). "Noteworthy, the homotetramer SOD2 (MnSOD) which is the most researched SOD in cancer is found exclusively in the mitochondrial matrix." (PMID 32774675, 2020). "Some studies have shown that the activity and expression of SOD2 in cancer cells are significantly down regulated as compared to that in control cells." (PMID 31929112, 2020). "The obtained results indicate that the examined antioxidants induced SOD2 activity in normal cells more effectively than in cancer cells." (PMID 31427965, 2019). "High levels of MnSOD gene (i.e., SOD2) expression have been found in different cancers and correlated to poor prognosis, low relapse-free survival and overall survival rate." (PMID 30934784, 2019). "FGF2 and CHEK4 are up-regulated while the expression of CHEK1, WT1, MDM2, BARD1, BMP2, BAMBI, and SOD2, have been reported to be down-regulated in several cancer subtypes, including CRC." (PMID 31623294, 2019). "Our studies revealed that the amount of SOD2 is significantly increased in normal cells treated with the tested antioxidants, whereas we observed a significantly increased levels of ROS among cancer cells." (PMID 31427965, 2019). "The mitochondria-localized manganese superoxide, SOD2, has a dichotomous role and aids in the regulation of several types of cancers." (PMID 31382449, 2019). "Mechanistically, hsa-miR-324-mediated inhibition of the SOD2-activated oncogenicity and the cancer stem cell-like phenotype of CRC cells is a probable critical component of our observed 4-AAQB—FOLFOX anticancer synergism." (PMID 30103475, 2018). "It has been shown that the up-regulation of SOD2 protein expression is characteristic of certain cancers, including cervical and salivary adenoid cystic carcinoma." (PMID 30103475, 2018). "There is likely a dichotomy whereas superoxide dismutase 2 (SOD2) can be considered a protective antioxidant, as well as a pro-oxidant during cancer progression depending on the level of accumulation and detoxification of H2O2." (PMID 29867559, 2018). "The findings indicate that SOD2 overexpression combined with radiation treatment can effectively inhibit the growth of HT-29 cancer cells in vivo." (PMID 27999194, 2017). "ROS accumulation in cancer cells induces expression of PGC-1å/ß to promote detoxification through direct induction of superoxide dismutase 2 (SOD2), catalase and glutathione peroxidase." (PMID 29100366, 2017). "It has become apparent that SOD2 transcription is dynamically regulated based on its context-dependent role in cancer." (PMID 29099803, 2017). "In the present work, the advantages of radiation-induced SOD2 overexpression in cancer therapy are as follows." (PMID 27999194, 2017). "Differential expression of SOD2 in cancer cells is in part due to the changes in relative abundance of Sp1 and AP-2." (PMID 29099803, 2017). "For more extensive reviews on the dichotomous function of SOD2 in cancer and mitochondrial redox signaling, we refer the reader to the following reviews." (PMID 29099803, 2017). "One of the proposed mechanisms of SOD2 downregulation in early stages of cancer involves aberrant patterns of cytosine methylation." (PMID 29099803, 2017).
cancer (continued). "In the next section, we will describe the post-translational modifications of SOD2 that have been explored in the context of cancers, leading to an imbalance in SOD2 protein or activity and consequential changes in mitochondrial redox homeostasis." (PMID 29099803, 2017). "Below, we highlight the major transcriptional mechanisms responsible for both inhibitory and activating SOD2 gene regulation in the context of cancer." (PMID 29099803, 2017). "This allows SOD2 to be either repressed or activated contingent on context-dependent stimuli, leading to its dichotomous function in cancer." (PMID 29099803, 2017). "Below, we focus on the regulatory mechanisms governing either activation or repression of SOD2 in cancer, ranging from transcription to posttranslational modifications." (PMID 29099803, 2017). "The HT-29 cancer cell proliferation in the SOD2 + Radiation (SOD2 + R) group was inhibited markedly with a nadir at 72 hours after radiation." (PMID 27999194, 2017). "While the transcriptional regulation leading to differential SOD2 expression has been the focus of much research, it is clear that the mechanisms of SOD2 post-translational regulation are less clearly delineated in cancer." (PMID 29099803, 2017). "All these SNP studies have emphasized the important roles of ALDH2 and SOD2 in alcohol drinking and smoking-induced cancer development." (PMID 28841898, 2017). "SOD2 protein was located in the cytoplasm and the expression of SOD2 was significantly higher in primary cancer tissues than in normal salivary gland tissues (P < 0.001)." (PMID 27181103, 2016). "Studies have shown that methylation of various regions in the SOD2 gene correlates with changes in MnSOD expression such as in ROS-rich cancer cells." (PMID 26989455, 2016). "We also found lower levels of the ROS scavenger SOD2 in reprogrammed stem cell-like cells vs. differentiated cancer cells." (PMID 27078845, 2016). "Although it is know that the lncRNA Lethe prevents binding of NFκB to NFκB response elements resulting in the suppression of SOD2, the impact of Lethe on energetic metabolism of cancer cells is poorly understood." (PMID 27551267, 2016). "It is suggested that the SOD2 biphasically modulates the cancer cells depending on its concentration and the specific context." (PMID 27023612, 2016). "Increased nitrosylation (4-HNE) and high SOD2 levels (indicating elevated oxidative stress) were observed in the muscle of cancer patients compared with those from HE." (PMID 27454226, 2016). "Altered SOD2 level has been reported in several cancer types, but the pattern is complex with down-regulation in some tumors but up-regulation in others." (PMID 27221200, 2016). "Consistent with published observations of decreased SOD2 expression in many cancers, we observed threefold lower expression of SOD2 in cancer specimens compared with benign breast tissue (p = 0.03)." (PMID 26316122, 2015). "The inflammation amplifier reflect genes associated with cancer development, and several genes from the amplifiers were found up-regulated in necrotic tumors, like PTGS2, IL6, SERPINE1 and SOD2." (PMID 26485755, 2015). "SOD1 stayed at similar levels, SOD2 expression increased in cancer, and SOD3 mRNA synthesis decreased correlating to reduced differentiation degree of thyroid tissue." (PMID 26664298, 2015). "In fact, the exact role of SOD2 and redox state in cancer onset and progression remains poorly understood." (PMID 25745358, 2015). "Elevated SOD2 levels have been observed in rodent lungs after inhalation of crocidolite asbestos and in several cancer cell types including gastric, colorectal, breast, and MM." (PMID 20831825, 2010). "Sod2+/- mice exhibit slightly increased rates of cancer butno other features of accelerated aging and have a normal lifespan." (PMID 20195488, 2009). "Reduced expression levels of SOD2 have been shown to result in increased DNA damage and sod2 heterozygous mice have increased incidences of cancer." (PMID 17895890, 2007).
cancer (continued). "In addition to the development of neoplastic alterations in human gastrointestinal tissues, SOD1 and SOD2 also have a role in the progression of tumors in the following sequence: benign tumor—malignant tumor—metastasis." (PMID 40867576, 2025). "Enhancing SOD2 activity, which reduces oxidative stress, may prevent DNA damage and hinder cancer development." (PMID 40244057, 2025). "Of note, we could observe that shSOD2 could re-sensitize these clones demonstrating the essentiality of SOD2-mediated protein degradation as an independent proteasomal protein degradation pathway in maintaining cancer cell fitness upon starvation." (PMID 40131931, 2025). "SOD2 overexpression has been shown to induce metabolic reprogramming in cancer cells." (PMID 40430023, 2025). "Specifically, two key enzymes—SOD1 and SOD2—protect cancer cells from oxidative damage." (PMID 40867576, 2025). "Furthermore, our study revealed significant modifications in HIF-1α and SOD2, two essential components involved in cancer cell survival and progression, particularly under conditions of hypoxia and oxidative stress." (PMID 39860164, 2025). "On balance, these findings are consistent with the hypothesis that SOD2 regulates cancer cell survival during amino acid starvation by its interaction with UBR2." (PMID 40131931, 2025). "We then asked how SOD2 inhibition sensitizes cancer cells to asparagine depletion." (PMID 40131931, 2025). "Conversely, disrupting the functional interplay between HIF-1α and SOD2 could render cancer cells more sensitive to oxidative stress, potentially improving the efficacy of therapeutic interventions." (PMID 39860164, 2025). "The roles of HIF-1α and SOD2 in cancer are context-dependent." (PMID 39860164, 2025). "Consequently, inhibition of SOD2-mediated protein degradation highly sensitizes different cancer entities, including patient-derived xenografts, to amino acid depletion, highlighting the pathophysiological relevance of our findings." (PMID 40131931, 2025). "Our study reveals that SOD2 is a regulator of proteasomal protein breakdown upon starvation, which serves as an independent catabolic source of amino acids, a mechanism co-opted by cancer cells to maintain cellular fitness." (PMID 40131931, 2025). "In addition, they showed that inhibition of SOD2 causes mitochondrial dysfunction and inhibits phosphorylation of the AMPK pathway, responsible for the survival of cancer cells." (PMID 39195258, 2024). "Our results indicate that SOD2 expression was higher in cancers than in normal pancreas." (PMID 37891871, 2023). "Manganese superoxide dismutase (MnSOD or SOD2) is strongly expressed in various cancers." (PMID 37446063, 2023). "However, further studies are needed to investigate the role of UHRF1 in the SIRT3/SOD2-Akt signaling pathway, which regulates various critical cellular processes required for cancer cell survival." (PMID 37630248, 2023). "Consequently, mice lacking both copies of the cytoplasmic superoxide dismutase 1 (SOD1) gene or having one copy deleted for the mitochondrial superoxide dismutase 2 (SOD2) gene exhibit noticeable oxidative harm and experience spontaneous cancer development." (PMID 37927596, 2023). "Although SOD2 has been shown to be phosphorylated at multiple residues, including S82 and S106, which residue is phosphorylated in cancer cells and what is the effect of the phosphorylation on SOD2 remain unknown." (PMID 37296072, 2023). "Additionally, SOD2 was recently found to have a novel epigenetic function promoting cancer cell plasticity where upon acetylation it was converted to a histone demethylase, then localized to the nucleus where it regulated the expression of Nanog and Oct-439." (PMID 37932310, 2023). "SOD2 overexpression in cancer cells could enhance the expression and function of MMPs, promoting matrix degradation and accelerating metastatic progression." (PMID 36497431, 2022).
cancer (continued). "Additionally, forced SOD2 overexpression in cancer cells is able to decrease the metastatic potential." (PMID 36009568, 2022). "Superoxide dismutase 2 (SOD2) has a dual role in cancer progression and metastasis." (PMID 36497431, 2022). "Furthermore, beyond our proof-of-concept study, we believe that SOD2 levels should be explored in the treatment of patients with advanced cancer." (PMID 36010852, 2022). "In several cancers, SOD2 expression is elevated during metastasis." (PMID 35164076, 2022). "Moreover, we reported decreased protein levels of SOD2, which have been shown to be strictly correlated to increased DNA damage and increased incidences of cancer." (PMID 35205361, 2022). "Consistently, it has been suggested that SOD2 has dual roles in cancer including HCC." (PMID 36430876, 2022). "The expression of CAT and SOD2 are involved in antioxidant system in various cancer cells." (PMID 33854627, 2021). "The expression of SOD2 in different cancers listed on the GEPIA website showed high values in KIRC." (PMID 34721758, 2021). "Studies conducted during the last decades indicate that SOD2 plays a dual role in cancer." (PMID 34062984, 2021). "As mentioned under the headings “Molecular characteristics in OCCCs related to anti-oxidative pathway” and “Oxidative stress and cancer stemness of OCCC,” molecules conferring oxidative stress resistance, including HNF1B, SOD2, and RDH10, are deeply implicated in therapeutic refractivity." (PMID 33525614, 2021). "SOD2 has been frequently reported mandatory for cancer stemness features." (PMID 34681918, 2021). "The regulation of SOD1 and SOD2 by the sample may affect the inflammation and cancer pathways, and some diseases have preventive and control effects." (PMID 34079813, 2021). "Thus, SOD2 can likely exert a protective effect on RR cancer cells by controlling potential ROS-mediated DNA damage via catalyzing the reduction of superoxide into less genotoxic molecules like oxygen." (PMID 33898418, 2021). "Furthermore, Superoxide Dismutase 2 (SOD2) in lightcyan module was proved to correlated with neutrophils infiltration in various cancer types." (PMID 33666342, 2021). "Our results raise the possibility of using SOD2 as a therapeutic target for malignant neoplasms." (PMID 34062984, 2021). "The intersection of differentially expressed genes (DEG) and our list of candidate genes, resulted in 12 elements including cancer associated genes (NRAS, MYC, and VEGFA), circadian drug targets (SOD2 and CES2) and core-clock and ECCN genes (AHR, CREB1, CSNK2A1, NFIL, NPAS2, NR1D1, and PER3)." (PMID 32295075, 2020). "miR-146a downregulates the expression of SOD2 and enhances ROS generation in cancer cells." (PMID 35006436, 2020). "However, lower SOD2 expression allows cancer cells to acquire beneficial DNA damages for enhanced proliferation and to obtain drug resistance mutations." (PMID 32372224, 2020). "SOD2 overexpression was related to metastatic phenotype in cancers." (PMID 32937815, 2020). "However, cancer cells expressing highly SOD2 can survive in a nutritionally depleted environment via preserving mitochondrial function and preventing ROS accumulation." (PMID 33092599, 2020). "Among pathways that are commonly altered in all three clusters, we find well-known factors contributing to carcinogenesis, such as those related to hypoxia (HIF-1, SOD2), cancer stem cells (CSCs), cell cycle proteins, like CDK family, signal transduction pathways and hormone signaling." (PMID 34316686, 2020). "The third biomarker, SOD2, is a primary mitochondrial antioxidant reducing reactive oxygen species (ROS), and which can prevent cell death and promote epithelial to mesenchymal transition and/or cancer cell migration." (PMID 33092599, 2020).